MTOR (mechanistic target of rapamycin kinase)
Diseases named in the same sentence as MTOR in open-access papers (continued):
Sharing a sentence is not in itself a finding about the gene and the disease.
tumor (continued). "Alterations in the PI3K/AKT/mTOR pathway have been associated with a variety of malignancies due to its well-documented involvement with development, cell growth, proliferation, malignant transformation, metastasis, tumor progression, apoptosis, and resistance." (PMID 36900412, 2023). "Moreover, inhibition of the PI3K/AKT/mTOR pathway could be associated with reducing tumor cell growth, proliferation, migration, invasion, and survival." (PMID 37046703, 2023). "Therefore, mTOR emerges as a potential player in FH-deficient tumours." (PMID 37689804, 2023). "Therefore, we concluded that S100a9 may inhibit MDS-associated tumor escape via PD-1/PD-L1 blockade through PI3K/Akt/mTOR signaling pathway activation." (PMID 36810783, 2023). "Therefore, the daily consumption of animal fats and red meat is correlated with increased cancer mortality, because these types of food induce the synthesis of IGF1 (insulin growth factor 1), an activator of the mTOR pathway which is associated with tumor progression." (PMID 37176098, 2023). "However, any consideration of enhancing tissue regeneration by manipulating the process needs to be careful, since hyperactivated mTOR signaling may cause repairing disorders, such as tumor formation." (PMID 38060073, 2023). "Therefore, MTOR is likely not only associated with immune cell function but also with tumor cell immunogenicity, suggesting that MTOR may play a central role in tumor immunity." (PMID 35883111, 2022). "Additionally, compared to normoxia, hypoxic tumor exosomes improved oxidative phosphorylation in macrophages derived from bone marrow via the transfer of let-7a miRNA, causing inhibition of the insulin-Akt-mTOR signaling pathway." (PMID 36233088, 2022). "High expression of STATs, HIF-1α, and mTOR has an important role in causing local hypoxia in tumors, forming a hypoxic barrier, tumor neovascularization, promoting tumor cell proliferation, and negatively regulating immunity and a series of other tumor-promoting events." (PMID 36119517, 2022). "Similarly, TSC2 mutations weaken mTOR regulation, leading to tumor cell proliferation and hypoxia." (PMID 36059442, 2022). "Increasing evidence has shown that aberrant activation of tumor-associated signaling pathways in many different tumors can induce tumor cells proliferation, metastasis and epithelial-mesenchymal transition, such as Wnt/beta-catenin signaling, Hippo signaling and mTOR signaling 9-11." (PMID 35982902, 2022). "Furthermore, mTOR inhibitors are associated with antitumor potential, which may be beneficial for tumor control." (PMID 36202608, 2022). "In addition, one case achieved a near CR within 18 months and found that the anti-oncogene TSC2 in this patient’s pretreated tumor tissue contained a somatic nonsense mutation that reactivated the mTOR pathway, which may reveal a mechanism of drug resistance." (PMID 36612173, 2022). "Agents that target the PI3K/AKT pathway may also prevent the transformation of premalignant gastric lesions into full malignancy, considering the mediator role of the PI3K/AKT/mTOR/HIF-1α axis in tumor-promoting inflammation in H. pylori- and EBV-associated GC." (PMID 35681691, 2022). "Besides, we speculated that the anti-tumor effects of LQ were associated with the inactivation of PI3K/AKT/mTOR pathway." (PMID 34488535, 2021). "Collectively, these findings revealed p-mTOR was identified as an independent predictor of poor survival, and mTOR was associated with tumor immune infiltrates in ccRCC patients, which validated mTOR could be implicated in the initiation and progression of ccRCC." (PMID 34458019, 2021).
tumor (continued). "As such, recently mTOR inhibitors, which include sirolimus (rapamycin), temsirolimus, and everolimus, have garnered favour because they have a lower association with de novo skin malignancies, and may in-and-of themselves have a direct anti-tumor effect." (PMID 34122442, 2021). "Besides antigen-encoding RNA, mTOR inhibitors also enhance the anti-tumor effects of DNA vaccines." (PMID 33802831, 2021). "The mutation of TSC2 may induce the formation of tumours by affecting mTOR inhibition." (PMID 34085405, 2021). "Therefore, by exerting an opposite effect on different pathways—inhibiting the TGF-β and RHOA/ROCK pathways, and activating PI3K/AKT/mTOR—miR-148a causes various functional consequences: It suppresses the development of metastases and increases the sensitivity of tumor cells to chemotherapy." (PMID 33142817, 2020). "Therefore, it is conceivable that a loss-of-function mutation with LOH of FBXW7 may cause overactivation of the mTOR pathway and promote tumor growth." (PMID 32429412, 2020). "Therefore, exploring the molecular mechanisms underlying mTOR upregulation and tumor progression may inform strategies to use anti-mTOR treatments in PCa." (PMID 32645691, 2020). "Despite their good performance in limiting tumor growth in preclinical and clinical studies, dose limiting toxicities such as diarrhea, skin rash, and an increase of transaminase have been found to be associated with pharmacological inhibitors of mTOR signaling." (PMID 31637215, 2019). "The Akt/mTOR signaling pathway may be implicated in the anti-tumor activity of sevoflurane." (PMID 31889892, 2019). "Interestingly, fibroblasts isolated from either TSC2 or REDD1-null mice exhibit increased proliferation rates and anchorage-independent growth under hypoxia as a result of aberrant mTOR activity, suggesting that loss of mTOR-dependent control of protein synthesis in hypoxia is tumour promoting." (PMID 30717305, 2019). "Finally, mTOR upregulation within the tumour is associated with increased tumour recurrence rates." (PMID 30650598, 2019). "Importantly, we observed a strong impairment of glucose metabolism when the combination with palbociclib and PI3K/mTOR inhibitors was preceded by treatment with palbociclib alone, likely contributing to the synergistic anti-tumor effects associated with this schedule of treatment." (PMID 29587820, 2018). "Furthermore, the miR-495-3p/GRP78/mTOR axis provides an insight into the mechanisms underlying tumor drug resistance and may serve as a novel therapeutic target for the treatment of MDR in GC." (PMID 30341283, 2018). "Consequently, in all four CRC cell lines tested, combination of AZ304 and Cetuximab caused a more potent inhibition of BRAF, ERK, AKT and mTOR signalling pathways, compared with single agents, providing a rationale for the observed synergy in anti-tumour effects." (PMID 29755114, 2018). "Therefore, the attenuation of mTOR signaling in the skeletal muscle of tumor-bearing mice might be caused by the activation of STAT3 signaling through the enhanced production of adipocyte IL-6." (PMID 30555329, 2018). "Furthermore, the PI3K/Akt/mTOR signaling pathway is associated with tumor metastasis." (PMID 30237403, 2018). "However, activation of the mTOR pathway can also result from mutations in either upstream class of genes: tumor suppressor and oncogenes depending on whether they activate or suppress pathway signaling." (PMID 29351204, 2018). "Thus, our results suggests that constitutive variation in the PI3K/AKT/mTOR pathway could result in alteration in susceptibility to toxicities caused by drugs inhibiting this pathway and also exert an effect in tumor outcome during treatment." (PMID 28727815, 2017). "Therefore, this study investigated whether the effect of sinularin on tumor cell proliferation is associated with the PI3K/Akt/mTOR pathway." (PMID 27472346, 2016).
tumor (continued). "Hence, the incidence of MTOR mutations may be much higher in metastatic tumor sites which would further support a role for this genetic alteration in tumor progression." (PMID 26255626, 2015). "Of interest, both rapamycin and the dual PI3K/mTOR inhibitor BEZ235 inhibited tumour growth in an Lkb1/Pten-deficient GEMM of endometrial cancer agreeing with a previous study that showed that single-therapy rapamycin effectively reduced tumour burden in Lkb1-deficient GEMM of endometrial ADC." (PMID 26196184, 2015). "Identifying the mTOR signaling transduction pathway clarified the molecular mechanisms that cause autophagy-mediated cell viability inhibition by antitumor agents and may contribute to the creation of novel therapeutic strategies for tumor growth suppression." (PMID 26168048, 2015). "By contrast, we observed a marked reduction in uptake in only one out of the three KPC mice, and this one response may reflect the transient reduction in proliferation that we observed by IHC in KPC tumours, or the possibility that the tumour may have acquired a mutation affecting mTOR signalling." (PMID 24717934, 2014). "The activated Phosphoinositide 3-kinase (PI3K)/AKT pathway stimulates mTOR to phosphorylate its downstream effectors p70 ribosomal S6 kinase (p70S6K) and eukaryotic initiation factor 4E binding protein 1 (4EBP1), mediating the expression of genes associated with tumor malignancy." (PMID 24866893, 2014). "Thus, gene expression analysis of patient tumours, using a very small set of probes, may prove valuable as a method by which to identify patients with deregulated mTOR signalling, particularly where there is loss of function, but not of expression." (PMID 24717934, 2014). "Thus, treatment with rapamycin is only effective in PTEN deficient tumours, suggesting that tumours with deregulated mTOR signalling may be uniquely sensitive to mTOR inhibition." (PMID 24717934, 2014). "The present findings reveal that resistance development towards the mTOR-inhibitor, everolimus, is associated with undesired feedback loops, including activation of the Akt/mTOR signaling pathway and increased cdk2/cyclin A expression, and is associated with cell cycle progression and tumor growth." (PMID 24935000, 2014). "Because the binding of insulin to its receptors activates the PI3K/AKT/mammalian target of rapamycin (mTOR) signaling cascade, activating mutations in the PIK3CA oncogene may determine tumor response to DR-like pharmacological strategies targeting the insulin and mTOR pathways." (PMID 23986086, 2013). "Since sirtuin 1 inhibits the mTOR pathway, we speculated whether H2A.Z downregulation due to sirtuin 1 overexpression might be mediated by repression of mTOR pathway, which is overactive and associated with tumor progression in PCa." (PMID 24127549, 2013). "Thus we assume that inhibition of mTOR activity by rapamycin may act a major brake on tumor development in Fbxw7 deficient mice." (PMID 23454868, 2013). "Likewise, mTOR inhibition could also be tested in our temporal controlled Pten-deficient tumor model and this will allow the dissection of mTOR pathway requirements when Pten is lost in systemic organs." (PMID 18043744, 2007). "Treatment options for AMLs include embolization and mTOR inhibitors such as everolimus, which can reduce tumor volume and improve cutaneous lesions." (PMID 41446687, 2026). "In conclusion, SIX5 functions as a critical oncogenic driver in GBM, regulated by KDM5C and promoting tumor progression through UBE2C-mediated activation of AKT/mTOR signaling and glycolytic reprogramming." (PMID 41939887, 2026). "Simultaneously, PI3K/Akt/mTOR synergizes with NF-κB by promoting IκB kinase phosphorylation and suppressing apoptosis, thereby fine-tuning immune responses, tumor metabolism, and ultimately influencing therapeutic efficacy." (PMID 41601649, 2026).
tumor (continued). "MTF downregulates the PI3K/Akt/mTOR signaling pathways and inhibits tumor cell proliferation in a wide range of tumors, some of them of hematologic origin." (PMID 41456173, 2026). "TSC2 functions as a tumor suppressor and is a critical negative regulator of the pro-oncogenic mTOR signaling pathway." (PMID 41522204, 2026). "TSC2 is a tumor suppressor gene that encodes the protein Tuberin complexing with Hamartin, the protein encoded by TSC1, and together they inhibit the mammalian target of rapamycin (mTOR) pathway, which is crucial for cell growth, metabolism, and proliferation." (PMID 41522204, 2026). "We discuss the roles of these molecules in key oncogenic signaling pathways, including PI3K/AKT/mTOR, Wnt/β-catenin, and Notch, and their contributions to tumor metabolic plasticity." (PMID 42278595, 2026). "In conclusion, this study reveals the GIPC1/TRIM21/TTC7B/mTOR/NF-κB tumor-suppressive axis in CRC and highlights the potential of GIPC1 for early diagnosis and overcoming chemoresistance in CRC patients." (PMID 41522336, 2026). "The features employed in constructing the PTEN and mTOR machine learning models in this study all encompassed peri-tumor data, with these features carrying substantial relative weight." (PMID 41602366, 2026). "These functional changes converge on key molecular pathways, including Wnt/β-catenin, NF-κB, and PI3K/Akt/mTOR, which regulate tumor cell proliferation, survival, and immune responses." (PMID 42197051, 2026). "The tumor suppressor PTEN is a key negative regulator of the PI3K/AKT/mTOR pathway and is frequently inactivated in NSCLC through genetic and non-genetic mechanisms." (PMID 42201046, 2026). "Reversal of differentiation is dependent on reduction of WNT pathway activation, Yap/Taz and MAPK signalling, which then enables activation of mTOR and the proliferative translatome that support tumour outgrowth." (PMID 41261129, 2026). "AKT suppresses autophagy and enhances tumor metabolism by activating mTOR via phosphorylation of the TSC1/2 complex, while phosphorylating pro-apoptotic factors BAD and BAX to inhibit apoptosis." (PMID 41481427, 2026). "Previous studies have demonstrated that RAP1A activates PI3K, leading to AKT phosphorylation and subsequent mTOR activation, which in turn regulates tumor resistance, proliferation, and survival." (PMID 41328352, 2026). "PD-L1 expression is considered to play a role in the protein kinase B (Akt)/mammalian target of rapamycin (mTOR) signaling pathway, which promotes the glucose metabolism of the tumor through the synthesis of glycolytic enzymes." (PMID 40668270, 2026). "Loss of STK11 disrupts AMPK signaling, leading to unchecked mTOR activation, metabolic reprogramming, angiogenesis, and epithelial-mesenchymal transition, fostering tumor progression and immune evasion." (PMID 42187558, 2026). "The mTOR signaling pathway, particularly mTORC1, serves as a key regulator of anabolic metabolism in tumor cells." (PMID 41328353, 2026). "Treatment with PF-309 for 3 h, 6 h, 12 h, and 24 h in WT cells consistently inhibited multiple pathways, including mTOR-S6K, NF-κB, c-Myc, and β-catenin, demonstrating its broad-spectrum anti-tumor effects." (PMID 41459112, 2026). "This axis appears to exert dual oncogenic effects: triggering paracrine M2 macrophage polarization to foster immunosuppression, whilst simultaneously fueling an autocrine TGF-β/TGFBR/PI3K/AKT/mTOR signaling loop to sustain tumor proliferation." (PMID 41880053, 2026). "HGF/cMET pathway activates cytoskeletal reorganization and invasion; PI3K/AKT/mTOR is involved in tumour cell survival and chemoresistance." (PMID 41476776, 2026). "FGF19 binding to FGFR and Klotho activates the mTOR pathway, promoting protein synthesis and tumor cell metabolism." (PMID 41328353, 2026). "Transient inhibition of mTOR during manufacture induces metabolic reprogramming and enhances anti-tumor activity of CAR T cells." (PMID 41720802, 2026).
tumor (continued). "GO nanoparticles also increase the affinity between β‐catenin and cadherin while downregulating the EGFR/AKT/mTOR and Wnt/β‐catenin signaling pathways in glioblastoma, thereby inhibiting tumor growth and invasion." (PMID 41573372, 2026). "Long non-coding RNAs (lncRNAs) including RHPN1-AS1 and PICSAR, in addition facilitate the activation of the PI3K/AKT/mTOR pathway through binding to tumour repressive miRNAs, e.g miR-7-5p or through upregulation of pathway components." (PMID 41476776, 2026). "The mTOR inhibitor Everolimus effectively suppressed tumour growth in an EF-colonied orthotopic model, highlighting its therapeutic potential for HCC patients with high EF burden." (PMID 42310938, 2026). "The aberrant activation of the PIK3/AKT/mTOR signaling pathway plays a critical role in sustaining tumor cell proliferation under these circumstances." (PMID 41496420, 2026). "These include the ERK/JNK/p38 MAPK cascade, the PI3K/AKT/mTOR axis, NF κB activation, and Wnt signaling, all of which collectively promote tumor initiation, survival, and metastasis." (PMID 42029494, 2026). "Examination of dabrafenib-treated BrafV600E/+;Rnf43fl/fl;Znrf3fl/fl lesions revealed a reduction in proliferation, mTOR signalling and tumour growth along with an upregulation of GLUL and a decrease in CDH1 and SOX9 levels." (PMID 41261129, 2026). "For instance, ADs weaken CSC properties by inhibiting the AKT/mTOR signaling axis, restore apoptosis sensitivity through modulation of the Bcl-2/Bax balance, and alleviate tumor-induced immunosuppression by blocking STAT3 signaling." (PMID 41599293, 2026). "Mechanistically, EF-derived extracellular vesicles (EF-EVs) deliver the bacterial GTPase Obg to activate the host mTOR pathway and drive tumour progression." (PMID 42310938, 2026). "The connections between Toll-like receptor (TLR) signalling, oxidative stress, and PI3K/Akt/mTOR are also investigated in relation to the possibility of encouraging tumour development in prostate conditions." (PMID 42158411, 2026). "For instance, in LUSC, a correlation exists between high FGF19 expression and mTOR activation, enhancing glucose and amino acid uptake, glycolysis, and oxidative phosphorylation to support tumor growth." (PMID 41328353, 2026). "Elevated extracellular K+ concentrations in the tumor microenvironment disrupt the intracellular K+ gradient, which in turn inhibits voltage-gated Kv1.3 channels and blocks the Akt-mTOR signaling pathway." (PMID 41438578, 2026). "Co-inhibition of mTOR and PIKfyve synergistically disrupts lipid and iron metabolism, leading to enhanced tumor suppression and improved survival in preclinical GEP-NET models." (PMID 41881024, 2026). "Silencing of SNHG10 decreases cell survival, proliferation, clonogenicity, EMT tumor growth through the EGFR/AKT/ERK/mTOR axis, and restores the expression of miR-150-5p, which eventually downregulates VEGF-A." (PMID 41916965, 2026). "Its expression is transcriptionally activated by the transcription factor TWIST, and it exerts pro-tumor effects by activating the PI3K/AKT/mTOR signaling pathway." (PMID 41836251, 2026). "Mechanistically, UBE2L3 downregulation led to increased tuberous sclerosis complex 2 (TSC2) expression, suppressing mTOR activity and altering autophagic processes in tumor cells." (PMID 41943836, 2026). "For example, in HCC, OCA has shown anti-tumor activity by reducing tumor and liver weights, as well as inhibiting the mTOR-S6K pathway." (PMID 41328353, 2026). "Targeting both the MAPK/ERK and PI3K/AKT/mTOR pathways will address compensatory mechanisms since synergistic inhibition of tumour growth has been demonstrated in preclinical models of CI-1040 and sorafenib." (PMID 41476776, 2026). "Meanwhile, the SSP forms an interactive network with tumor signaling pathways including Akt, mTOR, and EGF-ERK, collectively driving metabolic reprogramming." (PMID 41816347, 2026).